CXCL12 (C-X-C motif chemokine ligand 12)
Diseases named in the same sentence as CXCL12 in open-access papers (continued):
Sharing a sentence is not in itself a finding about the gene and the disease.
cancer (continued). "ER+ tumors are characterized by changes in the stromal compartment, with enrichment of endothelial cells (endo ACKR1, CXCL12, RGS5) and depletion of cancer-associated fibroblasts (iCAFs2 and myCAFs4), inflammatory monocytes (Mon S100A9), and B naive cells, compared with TNBC." (PMID 37549298, 2023). "Additionally, immunohistochemical staining of CXCL12 was conducted to assess the association between RHBDD2 and CXCL12 expression in fibroblasts surrounding carcinoma cells." (PMID 37264057, 2023). "In this setting, CXCL12 could establish a chemotactic gradient between the primary and metastatic sites, facilitating the transfer of CXCR4-positive cancer cells into tissues rich in CXCL12." (PMID 35729596, 2022). "Cancer-associated fibroblasts (CAFs) can inhibit both the innate and adaptive antitumor immune response by secreting numerous chemokines and cytokines, such as TGF-β, IL-6, IL-8, IL-13, CXCL12, CXCL14, and VEGFA." (PMID 35646893, 2022). "In contrast to what has been defined in cancer, the signaling pathways regulating CXCL12 and EC proliferation in PAH remain unclear." (PMID 36670936, 2022). "Also, CAFs secrete stromal cell-derived factor 1 (SDF-1 also known as CXCL12) which induces cancer cell drug resistance via a CXCR4, NF-κB and Bcl-xL-mediated signaling pathway." (PMID 35646668, 2022). "CXCL12 acts primarily via two mechanisms in cancer: (a) through an autocrine effect that promotes cancer cell growth, invasion, and angiogenesis, and (b) indirectly by recruiting cancer cells expressing CXCR4 into regions or organs containing CXCL12 to initiate metastasis." (PMID 35745762, 2022). "Attracted by CXCL12, cancer cells need 10 hours to extravasate through endothelium." (PMID 36439519, 2022). "Therefore, increased expression of the CXCR4/CXCL12 axis promotes cancer progression; hence patients with higher CXCR4 expression exhibit chemoresistance and reduced progression-free survival (PFS) and OS." (PMID 35269786, 2022). "PD-1 detection did not correlate with CXCL12, which is expressed by stromal cells, including cancer-associated fibroblasts supporting the specificity of our IHC assessment." (PMID 36009387, 2022). "Research shows that cancer tissues contain increased levels of CXCL12 and CXCR4." (PMID 36012171, 2022). "The KRT19+ cancer cells were specifically stained with anti-CXCL12 antibody." (PMID 35046049, 2022). "The significant KEGG pathways are chemokine signaling pathway (CCL5, CCL18, CCL19, CCL21, CXCL12, CXCL14, CXCL13), ​​NF-kappa B signaling pathway (CCL19, CCL21, CXCL12), intestinal immune network for IgA production (TNFRSF17, CXCL12), pathways in cancer (IGF1, CXCL12)." (PMID 35486660, 2022). "When considering the significant role of the CXCL12/CXCR4 axis in cell growth, proliferation, and migration, it is clear that the inhibition or blockade of CXCL12/CXCR4 holds promising therapeutic prospects for several diseases but especially for cancer therapy." (PMID 35893797, 2022). "It has been further demonstrated that there is a positive feedback loop between mTOR activation and the binding of CXCL12 to its receptor CXCR4—inhibiting the mTOR activity may prevent cancer metastasis because it subsequently decreases CXCL12 interaction." (PMID 36168036, 2022). "SDF-1 is an important niche factor in IL-7-expressing CAFs, indicating that the CXCL12 (SDF-1)/CXCR4 pathway may be a useful anti-cancer stem cell therapeutic (anti-CSC) target." (PMID 35735628, 2022). "Similarly, the overexpression of CXCL1, CXCL6, or CXCL12 has been shown to increase epithelial cell migration, proliferation, and growth, albeit in many cancer models." (PMID 35328555, 2022). "Therefore, the correlation between CXCR4/CXCL12 expression and cancer treated with CRT has been studied by many studies." (PMID 34976180, 2022). "That CXCL12 is cross-linked to KRT19 allows the heterodimer to self-assemble with KRT8, which is also secreted, into a higher-order filamentous network that coats the cancer cell." (PMID 35046049, 2022).
cancer (continued). "The CXCL12/CXCR4 axis is important in cancer progression and immunosuppression." (PMID 36010899, 2022). "Therefore, it is becoming recognized emerging that the CXCL12/CXCR4/CXCR7 axis represents a potential target for cancer treatment." (PMID 34976180, 2022). "Notably, CXCL12 secreted by cancer cells also protects preDC2 from macrophage-mediated IL-10-induced apoptosis." (PMID 35269786, 2022). "The CXCR4/CXCL12 and CCR5/CCL5 axes, both related to HIV, have been associated with the early (epithelial–mesenchymal transition and invasion) and late events (migration and metastasis) of cancer progression." (PMID 36613922, 2022). "This is because autocrine overexpression of CXCL12 in some tumors may be more sensitive to CXCR4 antagonists by competing with CXCL12 for receptor binding, meaning that they may be more suitable for the application of chemokine-based anti-cancer therapies." (PMID 35743888, 2022). "Interestingly, the impact of CXCL12 had been described to be involved in some forms of cancer as a pro-proliferative and pro-migratory factor." (PMID 36670936, 2022). "Also, simulation results succeeded to reproduce the behavior of SMAD7, TGFβ, LIF, and CXCL12 molecules in both cancer cell and CAF." (PMID 36171274, 2022). "The triggering of the CXCR4/CXCL12 signaling pathway enhances trans-endothelial migration and the homing and adhesion of cancer cells in the BM niche; it also increases the expression and excretion of other disease-progressing molecules (i.e., IL-6, integrins, and growth factors)." (PMID 35566637, 2022). "Interestingly, TAMs are reported to regulate the activation of CAFs by releasing CXCL12 and IL-6, thereby forming a positive loop to endorse cancer progression." (PMID 36324128, 2022). "CXCL12 is released from cancer and cancer-adjacent stromal cells, mainly from fibroblasts." (PMID 35203510, 2022). "Cancer cells of luminal BC communicate with immune cells through CXCL12_CXCR4." (PMID 36077333, 2022). "High expression levels of CXCL12, as well as VEGF are correlated with lymph node metastatic prostate carcinoma compared to non-lymph-node metastatic cancer and are associated with poor cancer-specific survival after radical prostatectomy." (PMID 35406450, 2022). "In addition, macrophages are attracted to CXCL12 secreted by CAFs and EOC cells, causing them to exhibit an M2 macrophage phenotype, thereby promoting cancer cell proliferation." (PMID 35269786, 2022). "Understanding how cancer cells attach CXCL12 to their surfaces, therefore, may identify a pathway that enables tumors to suppress the infiltration of T cells and evade T cell–mediated immune attack." (PMID 35046049, 2022). "Moreover, EPI-X4 antagonizes CXCL12-dependent signaling and migration of cancer and immune cells and serves as a CXCR4 inverse agonist as the peptide reduces basal G-protein signaling in the absence of the chemokine." (PMID 36499357, 2022). "CXC chemokine ligand 12 (CXCL12) has a critical impact on cancer development and metastasis." (PMID 34976180, 2022). "Our preclinical mouse model predicts that human cancer patients with low levels of CXCL12 and neutrophils could benefit from immunotherapies if they were treated concurrently with 7HP349." (PMID 35552271, 2022). "Thus, high CXCR4 expression in cancer stem cells (CSCs) will drive metastasis to tissues with high CXCL12 expression, such as the liver, lymph nodes, and bones." (PMID 35269786, 2022). "SKBR3 cancer cells were found to express Cxcl12 mRNA, which allowed an analysis of whether formation of the CXCL12–KRT19 heterodimer could occur in a cell-autonomous manner." (PMID 35046049, 2022). "CXCL12/CXCR4 axis had been proved to be associated with the progression and therapy of cancers." (PMID 36419891, 2022). "Cell adhesion molecules such as ICAM, B1 integrin, P-selectin, PECAM-1, CXCL12 and SDF-1 may also contribute to carcinoma metastases." (PMID 36497364, 2022).
cancer (continued). "Treatment outcomes are not yet universal, but one theory shows that this might be mediated through carcinoma-associated fibroblasts (CAF), which also influence the CXCR4/CXCL12 axis." (PMID 36059606, 2022). "CXCL12 further binds to CXCR4 on cancer cells, inducing EMT and promoting metastasis." (PMID 36046433, 2021). "Therefore, artificial overexpression of CXCL12 can rescue cancer cells in docetaxel and pexidartinib, which would otherwise be killed by CSF-1R inhibition." (PMID 34069563, 2021). "Furthermore, a recent study showed that PDAC excludes T cells and resists inhibitors of PD-1 checkpoints when cancer cells are coated with covalent heterodimers of CXCL12 and keratin 19 (KRT19) formed by transglutaminase-2 (TGM2)." (PMID 35008248, 2021). "We have shown that in early stages of cancer, immune‐regulatory CAFs recruit macrophages through a variety of signals including complement C3, CSF and CXCL12 and others have shown similar to CXCL12 and CXCL16, and via the CCL2–CCR2 axis." (PMID 32741067, 2021). "In support of this hypothesis, all affected proteins predicted on the basis of our mCRC‐specific deregulated miRNA dataset, most significantly NRG1 and CXCL12, are part of the pathways involved in cancer signalling and stem cell pluripotency." (PMID 34288395, 2021). "The migration of cancer cells to these organs is dependent on CXCL12 expression." (PMID 34298991, 2021). "Thus, a very important step has been the discovery of EPI-X4, which as a natural CXCR4 antagonist effectively blocks CXCL12-mediated receptor internalization and suppresses the migration and invasion of cancer cells towards a CXCL12 gradient." (PMID 33669329, 2021). "As for CXCL12, it has been extensively studied in the field of cancers." (PMID 33894748, 2021). "Therefore, we compared gene expression for cancer-associated fibroblast (CAF) markers including MMP2, MMP9, MMP21, TGFA, CXCL12, ITGA3, FAPα, and IL32 in fibroblasts derived from normal skin and MF tumors." (PMID 33941102, 2021). "While a combined inhibition of CXCR4 and CXCR7 may be advantageous for cancer treatment by more completely inhibiting CXCL12 signaling, more highly specific inhibitors may significantly reduce the side effects linked to small molecule inhibitors." (PMID 33530455, 2021). "The results showed that CXCL12 derived from fibroblasts significantly enhanced the invasion of cancer cells and the migration of vascular endothelial cells, and this enhancement could be blocked by CXCL12Ab and CXCR4siRNA." (PMID 34930323, 2021). "In conclusion, our study confirmed that pathways in cancer and gyroid hormone synthesis signaling pathway and two hub genes related to IS (CXCL12 and EIF2a) may be potential biomarker for accurate diagnosis and treatment of IS in future." (PMID 33880887, 2021). "Furthermore, the CXCL12/CXCR4 axis has been found to play an important role in anti-PD-1 resistance in other cancer types." (PMID 34911533, 2021). "This supports the theory that CXCR4 in cancer cells might be one of the critical docetaxel-resistance regulators and is potentially involved in CXCL12 (macrophage)/CXCR4 (cancer cell) crosstalk." (PMID 34069563, 2021). "Its ligand, C-X-C motif chemokine ligand 12 (CXCL-12), is constitutively produced by osteoblasts, fibroblasts, and endothelial cells to retain HSCs within the bone marrow, thus facilitating cancer cells aberrantly overexpressing CXCR-4 to migrate into the bone." (PMID 34360979, 2021). "Recent review articles related to C-X-C motif chemokine ligand 12 (CXCL12)-chemokine receptor type 4 (CXCR4)/ chemokine receptor type 7 (CXCR7) axis are focused on cancers in general, however, our focus in this review is to summarize the role of this axis in CRC progression and metastasis." (PMID 34298991, 2021).
cancer (continued). "On one hand, CXCL12 appears to be a critical chemokine for cancer cell dissemination; still, it may comprise a major chemokine/chemokine receptor mismatching mechanism for the trafficking of T cells into dissemination trajectories." (PMID 33927723, 2021). "In spite of the evidence that CXCR4 may be involved in docetaxel-resistance regulation, a direct link from CXCL12 by macrophage to CXCR4 in the cancer cells cannot be confirmed." (PMID 34069563, 2021). "Here, we propose that CXCL12 signaling in solid tumors can be effectively silenced with a well-tolerated drug with a large safety database that is currently in late-stage development for cancer." (PMID 35008248, 2021). "Similarly, cancer cell–expressed miR-454 inhibits the expression of stromal cell derived factor 1 (SDF1, also known as chemokine CXCL12)." (PMID 34591242, 2021). "Cancer-associated fibroblasts (CAFs) can produce epidermal growth factor (EGF), hepatocyte growth factor (HGF), fibroblast growth factor (FGF), IL-6, IL-8, chemokine C-X-C motif ligand 12 (CXCL12), and matrix metalloproteases (MMP-3 and MMP-9)." (PMID 33406763, 2021). "CXCL-12 promotes cancer cell proliferation as well as the angiogenesis." (PMID 34746270, 2021). "It has been known that CXCL12/CXCR4 axis plays a pivotal role in the neurotropism of cancer cells." (PMID 34170080, 2021). "Cancer stromal cells in PDAC abundantly express C-X-C Motif Ligand 12 (CXCL12)—A ligand of CXCR4." (PMID 33546207, 2021). "PDA-bearing mice display reduced response to immunological checkpoint antagonists because CXCL12 could coat cancer cells and shield them from T cells." (PMID 33407613, 2021). "The CAF product CXCL12 is an oncogenic chemokine that promotes many of the classical hallmarks of cancer and, as such, the cumulative effect of inhibiting it could provide significant clinical benefit." (PMID 35008248, 2021). "We then analyzed the effect of CXCL12 deletion on cancer progression." (PMID 33753872, 2021). "Strikingly, and consistent with our hypothesis, the overexpression of CXCL12 in the macrophages can remarkably enhance the survival of cancer cells despite the existence of pexidartinib." (PMID 34069563, 2021). "Our data indicate that ASC-derived CXCL12 promotes cancer progression in vivo." (PMID 33753872, 2021). "The baseline CXCL12 production in the metastatic cells might contribute to the generation of the chemokine gradient that attracts cancer cells to the site of the metastasis." (PMID 34834449, 2021). "The studies showed that the administration of AMD3100 (CXCL12 inhibitor) induced rapid T-cell accumulation in the region of tumor-containing cancer cells and performed synergistically with α-programmed cell death 1 ligand 1 (α-PD-L1) to greatly induce the apoptosis of cancer cells." (PMID 34681246, 2021). "The two receptors of CXCL12, CXC receptor 4 (CXCR4) and atypical chemokine receptor 3 (AKRC3, also known as CXCR7), are expressed on PDAC cells, and an elevated expression of CXCR4 is associated with a poor prognosis in several cancer types." (PMID 35008248, 2021). "To exclude the possibility that the decrease in cancer aggressiveness in KO mice was a result of systemic changes that could have resulted from CXCL12 deletion in stromal cells, we performed a systematic analysis of mouse anatomy and physiology." (PMID 33753872, 2021). "As the PPARγ ligand RGZ has been shown to interfere with this axis in other solid tumors, we evaluated whether the CXCL12/CXCR4 axis might contribute in mediating the ACC anti-cancer activity of RGZ in different ACC cell lines." (PMID 34834449, 2021). "Interestingly, elevated levels of secreted CXCL12 were detected in MAF supernatants, which is in line with other reports that describe an elevated CXCL12 production by CAFs in both human and murine carcinomas." (PMID 32328671, 2021).
cancer (continued). "Moreover, CXCR4 is a major receptor driving cancer metastasis, and not only the CXCR4/CXCL12 but also the CXCR4/MIF axis has been implicated in this process." (PMID 33239628, 2020). "For example, cancer chemotherapy upregulates CXCL12 and CXCR4 expression in multiple cancers." (PMID 33363463, 2020). "Cancer cells are thought to hijack the CXCR4/CXCL12 axis to establish distant metastasis." (PMID 32232002, 2020). "Our results indicate that CXCR4 and its ligand CXCL12 may not only serve as prognostic indicators in BC but may also play a role in the PPI network involved in cancer progression." (PMID 32228629, 2020). "Finally, CXCL12 has shown to directly promote radioresistance of several cancer types by different mechanisms, including sustaining stemness and inhibiting immunoresponse." (PMID 32854690, 2020). "We also emphasize the therapeutic targeting of the CXCL12 axis for cancer treatment." (PMID 33363463, 2020). "CCR5 and CXCL12 were selected due to their role in immune-response pathways in cancer patients." (PMID 33396862, 2020). "Cancer immunotherapy targeting CXCL12 axis are giving encouraging results." (PMID 33363463, 2020). "Several miRNAs (miR-25-3p, miR-130b-3p, miR-425-5p) upregulated in CRC cells by the CXCL12/CXCR4 axis could be transferred to macrophages via exosomes inducing M2 polarization of macrophages that promoted cancer metastasis by enhancing EMT." (PMID 32708431, 2020). "Importantly, CXCR4 is involved in the process of directing metastatic cancer cells to organs expressing CXCL12 and also supports the growth of cancer cells in distant metastasis." (PMID 32521759, 2020). "Although CXCL12 has initially been described as a homeostatic chemokine controlling angiogenesis, hematopoiesis and embryogenesis, a growing number of studies suggests its contribution to diverse pathologies including cancer." (PMID 33096815, 2020). "Indeed, CAFs are able to secrete factors, such as TGFβ and CXCL12, that directly stimulate cancer cell proliferation, EMT and migration." (PMID 31964880, 2020). "In this study, adaption of triple-negative breast MDA-MB-231 cancer cells to the CAF-secreted factors CXCL12 and IGF1 coincided with an increase in Src activity, which was then shown to be an result of an accumulation of pre-existing cells with a hyperactive Src pathway." (PMID 33228022, 2020). "Heparin can inhibit cancer metastasis by blocking the binding of CXCL12 and CXCR4." (PMID 32538273, 2020). "Some cancer therapeutics was developed to target CXCR4/CXCL12 signaling pathways." (PMID 33392074, 2020). "Therefore, higher CXCL12 levels in response to DPP4 inhibitor treatment can be relevant to the metastasis of CXCR4-positive cancers." (PMID 32498358, 2020). "The CXCR4/CXCL12 axis plays a crucial role in cancer metastasis." (PMID 32486408, 2020). "The aim of this study was to identify novel and potential inhibitors of CXCL12 that could be beneficial in limiting the cancer metastasis through various in silico techniques such as virtual screening, molecular docking, and molecular dynamic simulation." (PMID 33092204, 2020). "Furthermore, tissues with high CXCL12 expression, such as lymph nodes, liver and lung, are the most common cancer metastatic sites, and cancer cells migrate to these tissues in a CXCL12-dependent manner." (PMID 33392074, 2020). "The CXCL12/CXCR4/CXCR7 axis is a potential target for cancer therapies." (PMID 33363463, 2020). "Moreover, it was shown that activation of fibroblasts by cancer cells induced self-sustaining stromal cell-derived factor 1 (SDF1/CXCL12) and TGF-β autocrine signaling pathways to promote the formation of CAFs with increased α-SMA expression levels." (PMID 33228208, 2020). "Emerging evidence suggests that the chemokine, CXCL12, has a role in cancer metastasis." (PMID 32292657, 2020).